CLCNKA (chloride voltage-gated channel Ka)
Description:
Anion-selective channel permeable to small monovalent anions with ion selectivity for chloride > bromide > nitrate > iodide. Forms a homodimeric channel where each subunit has its own ion conduction pathway. May conduct double-barreled currents controlled by two types of gates, two fast gates that control each subunit independently and a slow common gate that opens and shuts off both subunits simultaneously. Assembles with the regulatory subunit BSND/Barttin for sorting at the basolateral plasma membrane domain and functional switch to the ion conducting state. CLCNKA:BSND channels display mostly a linear current-voltage relationship with fast gating at negative potentials. Mediates transepithelial chloride transport from the lumen to interstitial compartment along the thin ascending limb of Henle's loop, contributing to generation of hypertonic medullary interstitium as a countercurrent system to achieve urine concentration (By similarity). Conducts chloride currents in the stria vascularis of the inner ear to establish the endocochlear potential necessary for normal hearing.
Synonyms: hClC-Ka; ClC-K1; CLCK1
Tractability: Small molecule: it has a high-quality binding pocket; it belongs to a druggable protein family. Antibody: its Gene Ontology location is reachable by antibodies, with high confidence; UniProt places it where antibodies can reach, with medium confidence; UniProt predicts a signal peptide or a membrane-spanning region.
Gene: Protein-coding gene on chromosome 1 (16,018,146 to 16,034,109, forward strand). Ensembl gene ENSG00000186510.
Subcellular location: Basolateral cell membrane
Pathways (Reactome):
Transport of small molecules: Stimuli-sensing channels
Gene Ontology:
Molecular function: chloride channel activity; identical protein binding; protein binding; voltage-gated chloride channel activity; chloride transmembrane transporter activity
Biological process: chloride transport; renal absorption; transepithelial chloride transport; chloride transmembrane transport; transmembrane transport
Cellular component: basolateral plasma membrane; plasma membrane; membrane
Genetic constraint (gnomAD): Loss-of-function variants: 65 observed, 83.29 expected, observed/expected ratio (o/e) 0.78, 90% interval 0.64 to 0.96. The upper end of that interval is the gene's LOEUF score, 0.96, which puts it in group 4 of 6, group 1 being the genes least tolerant of losing a copy. Missense variants: 806 observed, 893.15 expected, observed/expected ratio (o/e) 0.9, 90% interval 0.85 to 0.96. Synonymous variants: 357 observed, 363.95 expected, observed/expected ratio (o/e) 0.98, 90% interval 0.9 to 1.07.
Homologues: Orthologues: chimpanzee CLCNKA (98% identical), dog CLCNK (88% identical), rabbit CLCNKA (86% identical), rat Clcnka (83% identical), mouse Clcnka (83% identical), mouse Clcnkb (81% identical), rat Clcnkb (80% identical), Drosophila melanogaster ClC-a (40% identical), Caenorhabditis elegans clh-3 (37% identical), Drosophila melanogaster ClC-c (24% identical), Caenorhabditis elegans clh-5 (23% identical), tropical clawed frog XB22062446 (19% identical). Paralogues in human: CLCNKB (91% identical), CLCN2 (45% identical), CLCN1 (41% identical), CLCN5 (24% identical), CLCN3 (24% identical), CLCN4 (24% identical), CLCN7 (23% identical), CLCN6 (21% identical).
Diseases named in the same sentence as CLCNKA in open-access papers:
CLCNKA is named in the same sentence as 36 diseases in open-access papers, as found by Europe PMC text mining. Sharing a sentence is not in itself a finding about the gene and the disease. The quoted sentences say what the papers report.
Bartter syndrome (8 papers, 2017 to 2025). "CLCNKA has been associated with Bartter syndrome type 4b [MIM #613090] through digenic inheritance in combination with CLCNKB variants." (PMID 32376988, 2020). "Yet, the combined loss of function of both channels causes a more severe type of Bartter syndrome, so-called Bartter syndrome type 4b (BS4b), suggesting that CLCNKA does have a complementary role in mediating chloride exit." (PMID 31664557, 2020). "Whole-exome sequencing (WES) excluded pathogenic variants in renal tubulopathy genes including SLC12A3 (Gitelman syndrome), SLC12A1, CLCNKB, BSND, KCNJ1, MAGED2 (Bartter syndrome), and CASR, CLCNKA, KCNJ10 (hypokalemia-associated genes)." (PMID 40893942, 2025). "Bartter syndrome is classified into five major genotypes caused by mutations in different genes, namely SLC12A1, KCNJ1, CLCNKB, CLCNKA, BSND, and MAGED2." (PMID 38238844, 2024). "In contrast, isolated loss of function of CLCNKA has not yet been associated with a clinical phenotype in man, despite actively looking for mutations in the gene encoding this transporter in unexplained cases of Bartter syndrome." (PMID 31664557, 2020). "GS is referred to as a mild variant of classic Bartter syndrome (or renal tubular normotensive hypokalemic alkalosis with hypercalciuria; MIM #607364), which is caused by defects in genes encoding chloride channel components, including CLCNKB, chloride voltage-gated channel Ka (CLCNKA), or both." (PMID 30999883, 2019).
heart failure (7 papers, 2017 to 2025). Inability of the heart to pump blood at an adequate rate to meet tissue metabolic requirements. "Furthermore, previous studies have demonstrated that CLCNKA plays a role in mediating chloride channels and is also implicated in heart failure and salt-sensitive hypertension, highlighting its potential as a therapeutic target in various diseases." (PMID 38817361, 2024). "When we clustered the results, one PPI cluster for LVEF is dominated by genes previously implicated with dilated cardiomyopathy and heart failure risk (HSPB7, FLNC, ALPK3, CLCNKA), as well as links to the brain via WDR7391–97." (PMID 39670392, 2025). "The GWAS of NT-proBNP levels identified cardiomyopathy- or heart failure-associated genetic loci (eg, HSPB7/CLCNKA, CDKN1A, TTN, FLNC, and BAG3)." (PMID 41054850, 2025). "In addition, CLCNKA has been reported to mediate chloride channel and found to be dysregulated in the heart failure and salt-sensitive hypertension." (PMID 32725165, 2020). "In our prior genetic analysis of the UK Biobank, we refined a heterogeneous heart failure phenotype to a specific, nonischemic cardiomyopathy subset, enabling detection of two DCM risk loci (near BAG3 and CLCNKA) that associated with subclinical changes in LV structure and function." (PMID 32382064, 2020).
diabetes insipidus (3 papers, 2018 to 2023). A disorder characterized by excretion of large amounts of urine, accompanied by excessive thirst. "Previous studies reported that biallelic variants in CLCNKA lead to a mild form of diabetes insipidus in knockout mice, but not in humans." (PMID 38069401, 2023). "However, research on CLCNKA knockout mice has revealed the presence of a mild form of diabetes insipidus." (PMID 38069401, 2023).
dilated cardiomyopathy (2 papers, 2019 to 2025). Cardiomyopathy which is characterized by dilation and contractile dysfunction of the left and right ventricles. "The variants in the CLCNKA and BAG3 loci for LVEF and LVESV were associated with dilated cardiomyopathy (DCM) (Table XI in the online-only Data Supplement)." (PMID 31554410, 2019).
glioma (2 papers, 2020 to 2024). A benign or malignant brain and spinal cord tumor that arises from glial cells (astrocytes, oligodendrocytes, ependymal cells). "Previously, it has been demonstrated that CLCNKA is associated with cancer stem cell characteristics of glioma." (PMID 38817361, 2024). "The previous study identified CLCNKA as a prognostic biomarker for glioma patients." (PMID 38817361, 2024). "Compared with CLCNKA and LOXL4, F2RL2 was specifically applied in all grades of primary glioma, revealing its prognostic role in primary glioma." (PMID 32725165, 2020). "Additionally, this in silico study also identifies three novel prognostic biomarkers (F2RL2, CLCNKA and LOXL4) for glioma patients." (PMID 32725165, 2020). "Additionally, we also identified three novel prognostic biomarkers (F2RL2, CLCNKA and LOXL4) for glioma patients in silico." (PMID 32725165, 2020). "Besides other eight reported biomarkers of glioma, we found that F2RL2, CLCNKA and LOXL4 were first identified as prognostic biomarkers for glioma." (PMID 32725165, 2020). "F2RL2, CLCNKA and LOXL4 are novel prognostic biomarkers for glioma which have not reported before." (PMID 32725165, 2020). "Finally, the 11 prognostic SRGs in the final multivariate model were validated by the CGGA data and we found three novel prognostic biomarkers (F2RL2, CLCNKA and LOXL4) for glioma that have not been reported before." (PMID 32725165, 2020).
hearing loss (2 papers, 2020 to 2023). "The current case suggests that an additional copy gene defect in CLCNKB, in combination with biallelic loss-of-function alleles in CLCNKA, contributed to the development of the hearing loss phenotype." (PMID 38069401, 2023). "Review of the ES data for rare variation in genes associated with hearing loss revealed one heterozygous shared variant in CLCNKA (NM_004070.3:c.820G>A; p.Asp274Asn)." (PMID 32376988, 2020). "The distinct presentation of non-syndromic hearing loss in the case involving a single copy loss of CLCNKB along with biallelic loss-of-function alleles in CLCNKA might be understood through the differential roles that these genes have in the inner ear and kidney." (PMID 38069401, 2023). "In the literature review, among the spectrum of clinical phenotypes reported for variants of the CLCNKA and CLCNKB, those associated with hearing loss are primarily linked with Type III or Type IV BS." (PMID 38069401, 2023).
Hypokalemia (2 papers, 2025). An abnormally decreased potassium concentration in the blood. "Type IVa and IVb involve mutation BSND and CLCNKA genes, respectively, with polyhydramnios, sensory deafness, hypokalemia, and hypochloremic alkalosis as prominent features." (PMID 40666068, 2025).
angiosarcoma (1 paper, 2016). A malignant tumor arising from the endothelial cells of the blood vessels. "Interestingly, expression of one Cl− channel (namely CLCNKA) is strongly modified in angiosarcoma vs controls." (PMID 27716384, 2016).
Bartter syndrome type 4 (1 paper, 2024). A form of Bartter syndrome characterized by maternal polyhydramnios, premature delivery, salt loss, polyuria and sensorineural deafness, associated with hypokalemic and hypochloremic metabolic alkalosis, increased levels of plasma renin and aldosterone, and low to normal blood pressure. "Bartter syndrome type 4 is a disease in which both CLCNKA and CLCNKB are affected and was found to be associated with biallelic pathogenic mutations of the BSDN gene, coding for the essential Barttin subunit of both the CLCNKA and CLCNKB chloride channels." (PMID 38731822, 2024).
deafness (1 paper, 2020). An inherited or acquired condition characterized by the complete loss of the ability to hear from one or both ears. "One interesting and challenging aspect is the number of digenic inheritance reports following the initial case of Bartter syndrome and deafness caused by inactivating biallelic mutations in both CLCNKA and CLCNKB." (PMID 32150856, 2020). "Interestingly, only homozygous inactivating mutations in each of the two chloride channels, CLCNKA and CLCNKB, have been associated with deafness, perfectly overlapping with the definition of true digenic effects." (PMID 32150856, 2020).
diabetic retinopathy (1 paper, 2018). "This region spans genes with plausible roles in the development of diabetic retinopathy, (e.g. PADI1, PADI2, PADI3, and PADI4, as well as genes known to be involved in kidney function (CLCNKA and CLCNKB)." (PMID 29444168, 2018).
glioblastoma (1 paper, 2024). The most malignant astrocytic tumor (WHO grade IV). "Our findings suggest that CLCNKA participates in disulfidptosis, which may represent a novel therapeutic target for glioblastoma." (PMID 38817361, 2024).
sensorineural deafness (1 paper, 2023). "Moreover, the presence of two loss-of-function alleles in both ClC-K channels (CLCNKA and CLCNKB), as a digenic trait, leads to severe renal salt wasting and sensorineural deafness, which is classified as type IV BS." (PMID 38069401, 2023).
teratoma (1 paper, 2024). A non-seminomatous germ cell tumor characterized by the presence of various tissues which correspond to the different germinal layers (endoderm, mesoderm, and ectoderm). "However, only amplifications of CLCNKA and CLCNKB on 1p36.13 were noted in most (6/9) teratomas in this study." (PMID 38907278, 2024).
renal disease (1 paper, 2022). "For example, ion channel (CLCNKA and CLCNKB) and transporter (SLC12P6) alteration, which act in concert to regulate volume and ionic concentration by absorption or secretion of ions into the urine, leads to renal disease." (PMID 35055008, 2022).
CLCNKA also shares sentences with these, for which no sentence is quoted: cardiomyopathy (3 papers); tumor (3); cancer (2); hydronephrosis (2); nephrogenic diabetes insipidus (2); Alkalosis (1); Blindness (1); gastric cancer (1); gestational diabetes mellitus (1); Gitelman syndrome (1); Hypercalciuria (1); Hypertension (1); kidney damage (1); left ventricular noncompaction (1); leukodystrophy (1); Miscarriage (1); Polyuria (1); renal clear cell carcinoma (1); renal tubular disease (1); Sepsis (1); sterility (1).